CD4 (CD4 molecule)
Diseases named in the same sentence as CD4 in open-access papers (continued):
Sharing a sentence is not in itself a finding about the gene and the disease.
cancer (continued). "While humoral immune responses were lower in HPV+ cancer patients, higher humoral immune responses were associated with CD4+ T cell-dominated immune infiltrates." (PMID 32146518, 2020). "As a critical participant in immune escape, the CD4+ T cell subset of regulatory T (Treg) cells, with their immunosuppressive functions, has been implicated in the occurrence of many types of cancers." (PMID 32425930, 2020). "Our results revealed that BCs with high mutation rates, although the mutation rate was far lower than in other cancer types, have attracted effective immune cells in their microenvironment, such as macrophage M1 and CD4 + T cells." (PMID 32024876, 2020). "The HIV‐specific variable associated with non‐oropharyngeal HNSCC was nadir CD4 count, which was associated with an increased risk of cancer." (PMID 33094910, 2020). "The resultsshowed that co-culturing naïve CD4+ T cells with cancer-ASCs and normal-ASCs caused decreased population ofCD4+CD25+FOXP3-Helios+ in comparison with the controlgroup (P=0.028 and 0.028, respectively)." (PMID 31721539, 2020). "The massive expansion of CD8 + T cell actively depends on interferon alpha (IFNα), which improves prognosis by causing cancer cell cycle arrest, whereas CD4 +, which is related to IFN-γ, is associated with poor prognosis in patients with cancer." (PMID 32512904, 2020). "It was associated with an increased frequency and absolute number of CD4+Foxp3+T regulatory (Treg) cells, an immunosuppressive cell which is frequently associated with poor prognosis in cancer." (PMID 32823603, 2020). "A recent analysis of antigen-specific immunity in cancer patients revealed that CD4+ T cells efficiently recognized mutated neoantigens in melanoma." (PMID 32708397, 2020). "The activation and functional status of CD4+ T cells is important for adequate responses to pathogen infections but has also been associated with auto-immune disorders and survival in several cancers." (PMID 33383959, 2020). "While CD8 T cells are associated with a favorable outcome in most cancers, only T helper type 1 (Th1) CD4 T cells play a protective role, in contrast to Th2 CD4 T cells." (PMID 30984190, 2019). "Multivariate cox analysis showed that frequency of CD4+CD45RChigh below 51.9% was significantly associated with cancer after adjustment on age, gender, and induction therapy (HR 3.71, p = 0.019)." (PMID 30925186, 2019). "The link between reduced CD4 count and elevated cancer risk is profound in KS and NHL, but also present in other malignancies." (PMID 31555284, 2019). "Several cellular markers have been associated with the development and/or function of CD4-CTLs in the setting of persistent viral infection or cancer." (PMID 31308093, 2019). "CD4+ T-cells make up the largest lymphocyte subset in human BM, and reduction of CD4+ T-cell levels in BM is associated with many infections and cancers." (PMID 31657719, 2019). "Given that a high frequency of CD8+CD45RChigh was associated with AR occurrence and that a low frequency of CD4+CD45RChigh was associated with cancer occurrence, we next analyzed if CD45RC expression on CD4+ and CD8+ T cells were associated." (PMID 30925186, 2019). "We observed that patients with a low pre-transplant proportion of CD4+CD45RChigh, or accordingly, patients with a high proportion of CD4+CD45RClow T cells had a greater risk of developing cancer after transplantation." (PMID 30925186, 2019). "Lower CD4 cell count nadir showed a strong association with risk of incident virus-associated cancers (adjusted HRs/100 cells/μl decrease [95% CI] 1.31 [1.13, 1.51]; p < 0.001)." (PMID 30315476, 2018). "In this longitudinal case–control study of HIV-uninfected men with median 21 years of follow-up, low CD4 T-cell count and nadir and low CD4:CD8 ratio nadir were associated with increased risk of virus-associated cancers (p ≤ 0.002 in Cox hazard models)." (PMID 30315476, 2018).
cancer (continued). "In the last few years CD4+/CD8+ T cell neoepitopes originated from cancer mutations are emerging as key targets for cancer immunotherapy." (PMID 30416985, 2018). "NF-κB has been shown to regulate the transcription of genes encoding Bcl-2 and Bcl-xL in other cell types such as cancer cells and CD4+ T lymphocytes." (PMID 29848490, 2018). "An incident diagnosis of virus-associated cancer was associated with lower CD4 cell and white blood cell counts in models adjusted for age, race, heavy smoking, and FIB-4 scores > 1.45 (p = 0.001 and 0.032, respectively)." (PMID 30315476, 2018). "Although PD-1 function is frequently associated with CD8+ T cell responses towards virus and cancer antigens, the results presented here as well as several earlier studies underline that PD-1 signals can keep CD4+ T cells in check." (PMID 30201974, 2018). "Low CD4 count-nadir differential (adjusted HR [95% CI] 1.27 [1.09–1.48]) was a stronger predictor of incident virus-associated cancers than recent CD4 count." (PMID 30315476, 2018). "The strong negative selection of an MHC class II modulator is compelling given recent evidence highlighting the importance of (MHC class II-binding) CD4(+) T cells in recognizing immunogenic mutations in cancer genomes." (PMID 29855388, 2018). "More recently, exogenous IL-21 was shown to inhibit the expression of FoxP3, the cardinal transcription factor associated with regulatory T cells, in human CD4+ T cells following encounter with cancer cells – in a manner similar to TGF-β blockade." (PMID 29854291, 2018). "FOXP3+ T cells are common regulators of cytotoxic T-cell responses, and high levels of peripheral CD4+CD25+FOXP3+ regulatory T cells have been associated with poor clinical response to adoptive cell therapy in human cancer." (PMID 29930558, 2018). "In Cox hazard models, low CD4 cell count and nadir were associated with increased hazard of virus-associated cancers (adjusted HRs [95% CIs] 1.17 [1.03–1.33], and 1.3 [1.13–1.5], respectively)." (PMID 30315476, 2018). "The appearance of cytolytic CD4+ cells can be linked to repeated antigen exposure in chronic infection and in cancer bearing individuals reflecting a senescent immune system." (PMID 30323982, 2018). "In HIV mono-infected patients, the most frequent non-AIDS-related cancers are oncogenic virus associated malignancies such as EBV and HPV, and low CD4 counts have been associated with a higher risk of these cancers." (PMID 30562358, 2018). "The incidence of ADCs is higher when patients have lower CD4 cell counts, initially present with cancer or revisit after loss to follow-up." (PMID 30409111, 2018). "In summary, our study shows that HIV-seronegative MSM with low nadir CD4 counts or low CD4:CD8 ratio nadirs have elevated risk of developing virus-associated cancers within a 6-year time window." (PMID 30315476, 2018). "Coincidentally, a higher CD8+ to CD4+ T cell ratio has been associated with better patient prognosis in several cancers." (PMID 29513764, 2018). "While, chemoradiation was recently found to upregulate PD1 expression on both CD8 ad CD4 T cells, the status of PD-L1 on cancer-associated myeloid cells, such as MDSCs, was uncharacterized." (PMID 29541413, 2018). "In HPV-associated cancer, targeting co-induction of broad CD4 and CD8 T-cell responses correlated with vaccine efficacy." (PMID 29740440, 2018). "In fact, over 90% of cancer cell mutations recognized by CD4+ and CD8+ T-cells occur in passenger genes." (PMID 28100240, 2017). "Nevertheless, Overwijk found that each person’s naive CD4+ T cells spontaneously responded to neoepitopes or peptides derived from cancer proteins encoded by mutated genes." (PMID 28488173, 2017). "Cancer risk has also been shown to undergo changes during ART depending on cluster of differentiation 4 (CD4) cell count and HIV viral load (VL) modification." (PMID 27603338, 2016).
cancer (continued). "The prominent role of CD4 nadir as risk factor for ADM also emerged in the analysis considering only cancers that occurred after ART initiation." (PMID 27603338, 2016). "This important finding has been shown in other cancer sites where loss of CD4+ Treg and TIL numbers at the margins of liver metastases predicted for response to chemotherapy." (PMID 27020682, 2016). "To date, the only association between CD4 count and the relative risk of developing a malignancy has been shown in cancers with a known viral pathogenesis, the so-called AIDS-defining cancers." (PMID 28717714, 2016). "Our analysis showed actually that the effect of immune restoration and/or CD8+ T cell activation was quite different according to the type of event with an independent role of the CD4/CD8 ratio evidenced only on the risk of cancer." (PMID 27548257, 2016). "The authors of this study found an association between high levels of CD4+ T cells in cancer stroma and longer survival." (PMID 26871598, 2016). "In that study, malignancies and infections were the primary causes of death, and both occurred more frequently in patients with a CD4 count <200 cells/μL." (PMID 27025828, 2016). "Independently of CD4+ cells count, the risk of cancer was indeed twice higher in the subset of patients who had a CD4/CD8 ratio below 0.5." (PMID 27548257, 2016). "The hallmark of untreated HIV disease is progressive loss of CD4+ T cells, chronic inflammation, and generalized immune dysfunction, all leading to loss of immune control of multiple pathogens and cancers." (PMID 24391889, 2013). "Women with a CD4 count of 650 per mm3 or more also had lower risk of screening positivity or invasive cancer diagnosis (RR=0.3, 95%CI=0.2–0.6)." (PMID 23767681, 2013). "A higher CD4 count at diagnosis was associated with improved survival for some cancers, and when considering NADC jointly." (PMID 24106926, 2013). "For example, in Rwanda, an inverse association was found between the CD4 count and cervical pre-cancer among HIV-infected women." (PMID 23767681, 2013). "Women with a CD4 count of 650 per mm3 or more had the lowest risk of screening positivity or invasive cancer diagnosis (RR=0.3, 95%CI=0.2–0.6)." (PMID 23767681, 2013). "To investigate the role of TSAd in CD4+ T cell mediated cancer immunosurveillance, we crossed SH2D2A-deficient mice with idiotype (Id)-specific TCR-transgenic mice." (PMID 23144743, 2012). "We are currently implementing a prospective cohort of HIV controllers designed to determine the long-term prognosis, including changes in the CD4 cell count and viral load, and the risk of cancer." (PMID 21533035, 2011). "Depending on the particular model, CD8, CD4, DC and NK cells have all been implicated in anti-4-1BB therapies of cancer based on such immunodepletion studies prior to treatment." (PMID 20543982, 2010). "Persistent infection and cancer progression is also associated with abnormal response of CD4+ T cells and CD8+ T cells." (PMID 19087272, 2008). "On multivariate analysis, grade (HR 2.47, 95% CI 1.37–4.46, P<0.01) and percentage CD4+ (HR 4.44, 95% CI 1.87–10.57, P<0.001) were independently associated with cancer-specific survival." (PMID 14612901, 2003). "In addition, there were a limited number of cancer cases following KS diagnoses, and data on CD4 cell counts, HIV treatment status and other risk factors including smoking and family history of cancer were not available." (PMID 41546776, 2026). "Hence, patients with cancer under active antineoplastic treatment presented with a more rapid loss of vaccine-mediated protection, especially evident at the level of CD4+ responses." (PMID 41210962, 2025).
cancer (continued). "Interestingly, though TLSs are generally associated with a favorable prognosis in some cancers 204, in aged mice, TLSs promoted by CD4+ T cells led to ICB resistance." (PMID 40860134, 2025). "Additionally, platelet-thrombocyte aggregates (PTAs) are associated with an increased risk of thrombosis, with cancer patients exhibiting significantly higher percentages of PTAs among CD4+ and CD8+ T lymphocyte populations compared to healthy individuals." (PMID 40552264, 2025). "Additionally, by secreting various adipokines, cancer-associated fibroblasts contribute to the downregulation of CD4+ memory T-cells and CD8+ cytotoxic T-cells, and boost the recruitment of M2 macrophages and fibrosis in the adipose tissue." (PMID 39858017, 2025). "Additionally, anti-CD4 mAb + GST-CD4 exhibited a notable reversal of the expression of naive CD4 + T cells, epithelial-to-mesenchymal transition (EMT), and cancer-associated fibroblast (CAF) markers in mice treated with anti-CD4 mAb." (PMID 40542350, 2025). "However, with the cancer progression and development of immunosuppressive TIME, the anticancer action of CD4+CTLs decreases, and their increased number is associated with prolonged survival of patients with cancer, including high-risk neuroblastoma patients." (PMID 41009359, 2025). "Although its role in Tfh biology has been underappreciated to date, GNG4 expression has appeared in DEG analyses of human T cells, including Tfh, thymic CD8αα T cells, cancer-associated subsets, and was listed after mass spectrometry studies of CD4 T cells stimulated in vitro." (PMID 41427421, 2025). "Second, by turning the entire polyclonal population of CD4+ Tregs towards the tolerogenic pathway we can halt the immune response to cancer cells, viruses, pathogenic bacteria and other agents normally destroyed, so the next step will be the creation of antigen-specific iTregs." (PMID 40650152, 2025). "HIV-1 viremia may increase cancer risk indirectly through CD4 depletion or more directly through chronic inflammation, accelerated immunosenescence, and direct pro-oncogenic effects of HIV-1." (PMID 39736138, 2025). "Adjusting for CD4 count as a potential mediator may also have introduced collider bias if other unmeasured factors are associated with both CD4 count and cancer risk." (PMID 39736138, 2025). "Mechanistically, the recognition of BCG antigens by CD4+ T cells via HLA class II molecules expressed on cancer cells could be a key factor underlying the antitumor effect of BCG." (PMID 41312368, 2025). "People living with HIV who have a narrower CD4:CD8 ratio are at higher risk of developing cancer." (PMID 40099965, 2025). "In addition, CENPA is significantly correlated with the infiltration of several immune cells, mainly including Th2/1 CD4 + T cells, stroma-score and cancer- associated fibroblast." (PMID 40804263, 2025). "However, this study reveals the novel biomarkers of cancer cells, CD8+ NKT-like cells, memory CD4+ T-cells, and naive CD4+ T-cells implicated in T-cell exhaustion, inducing the growth, proliferation, and progression of cancer cells." (PMID 40906153, 2025). "Tregs, a subset of CD4+T cells expressing Foxp3, play critical roles in suppressing immune responses and migrating toward tumors in the presence of chemokines to suppress antitumor immune responses, causing cancer cells to grow and proliferate." (PMID 40563656, 2025). "Although cancer vaccines would ideally seek to elicit a cytotoxic T-cell response, measuring cancer-antigen-specific antibody release can act as a marker for effective immune response due to overlap with the underlying CD4+ repertoire needed for activating cytotoxic CD8+ T-cells." (PMID 40438385, 2025). "Thus, older PLWHIV with low CD4 counts represent a particularly high-risk group for cancer development." (PMID 41295583, 2025).
cancer (continued). "In response to IL-23 (a kind of pro-inflammatory cytokine), IL-17 is released by pathogenic CD4+ Th17 cells that activate multiple signaling mechanisms by binding to complex receptors, which may have differing roles in cancer progression." (PMID 41376623, 2025). "Significant differences in the levels of immune cell subsets including NK cells, B cells, myeloid dendritic cells, cancer-associated fibroblasts, macrophages, mast cells, CD4 + T cells, CD8 + T cells, and regulatory T cells were observed in different groups of immune cell subsets." (PMID 38688945, 2024). "Notably, CD4 nadir has been recently shown to be associated with cancer progression among people with HIV." (PMID 39770774, 2024). "Most notably, hematopoietic stem cells (P < 0.001), monocytes (P < 0.001), and cancer-associated fibroblasts (CAFs) (P < 0.001) displayed greater abundance scores in S-T1 tumors, while Th1 CD4 + T cells (P < 0.001) exhibited greater abundance scores in S-T3 tumors." (PMID 39568014, 2024). "Our findings suggest that impaired immune surveillance indicated by low CD4 cell count may impede the body’s capacity to identify and eradicate malignant or pre-malignant cells and therefore play a role in increased cancer risk among HIV-infected workers." (PMID 39042631, 2024). "The different binding receptors of RNase1 on macrophage and CD4+ T cells might cause the differential responses in the two cell and cancer types." (PMID 38307859, 2024). "Correlation analysis shows PGAM1 expression correlates with infiltration levels of various immune cells including macrophages, natural killer cells, myeloid dendritic cells, monocytes, cancer-associated fibroblasts, mast cells, neutrophils, B cells, CD4+ T cells, CD8+ T cells and regulatory T cells." (PMID 38434965, 2024). "The proportions of infiltrating B cells (p = 0.0012), cancer-associated fibroblasts (CAFs) (p = 5.1e−16), CD4+ T cells (p = 1.9e−08), endothelial cells (p = 5.4e−08), and macrophages (p = 7.6e−15) significantly increased in the high-risk group compared to the low-risk group." (PMID 38696324, 2024). "Clonal proliferation of HIV-1-infected CD4 T cells harboring proviruses integrated into proliferation- or cancer-associated genes has been documented before and may reflect accelerated cell growth resulting from retroviral insertional mutagenesis." (PMID 39466203, 2024). "The TIDE analysis highlighted specific immune cell changes associated with responders, including an increase in CD4+ TILs (P < 0.05) and macrophages (P < 0.05), and a concurrent decrease in cancer-associated fibroblasts (CAFs, P < 0.01) and endothelial cells (P < 0.01)." (PMID 39024554, 2024). "Importantly, YAP1, the AR, and the PSA were strongly associated with CD4+/CD8+ T cells in PC compared with other cancers (respectively)." (PMID 38540274, 2024). "Bubble plots showed that hematopoietic stem cells, cancer-associated fibroblasts, and myeloid dendritic cells were negatively correlated with the risk score, whereas CD4+ Th1 T cells, CD4+ Th2 T cells, and common lymphoid progenitors were positively associated with the risk score." (PMID 39132150, 2024). "PAN2RS was significantly and positively associated with the infiltration of CD4 T cells, Tregs, and M2 macrophages while negatively associated with the infiltration of NK cells, memory B cells, and Th1 cells across cancer types, consistent with the previous conclusion." (PMID 38322112, 2024). "Conversely, CD4 memory‐activated T cells, follicular helper T cells and regulatory T cells (Tregs) were highly expressed in the high‐risk group, indicating a more activated state of the immune system, possibly attempting to combat cancer development." (PMID 39031800, 2024). "In addition, infiltration of CD4 + T cells, cancer-associated fibroblasts, macrophages, and endothelial cells were associated with CDKN3 expression in various tumors." (PMID 38720365, 2024).